GDF15 (growth differentiation factor 15)
Diseases named in the same sentence as GDF15 in open-access papers (continued):
Sharing a sentence is not in itself a finding about the gene and the disease.
sarcopenia (continued). "This review describes the principal pathways controlling mitochondrial quality, many of which are potential therapeutic targets against muscle aging, and the connection between mitochondrial dysfunction and the myomitokines FGF21 and GDF15 in the pathogenesis of aging sarcopenia." (PMID 33374852, 2020). "The GDF-15 levels were significantly higher in sarcopenia patients." (PMID 31581569, 2019). "From these results, it is very likely that circulating preoperative GDF-15 level may be a biomarker for identifying muscle wasting and sarcopenia in cardiovascular surgery patients." (PMID 31581569, 2019). "However, the use of circulating GDF15 (c-GDF15) as a biomarker of sarcopenia is still debated." (PMID 38808117, 2024). "Consequently, elevated GDF-15 level may potentially influence the development of sarcopenia and the occurrence of advanced liver fibrosis." (PMID 39498408, 2024). "Furthermore, systemic GDF‐15 levels could predict the presence of sarcopenia in a validation cohort with good prognostic accuracy." (PMID 38890783, 2024). "However, whether circulating GDF15 levels can be used for the prediction of sarcopenia in patients with COPD is unknown." (PMID 35845807, 2022). "Importantly, serum levels of GDF15 could effectively predict sarcopenia in patients with COPD based on the development set (AUC = 0.827) and validation set (AUC = 0.801)." (PMID 35845807, 2022). "The strengths of this prospective observational study are that we showed that the serum GDF15 level is simple and useful as a screening test for sarcopenia in patients with COPD and nomogram model based on GDF15 level and clinical features could further improves the predictive ability." (PMID 35845807, 2022). "Therefore, more evidence is still needed to confirm whether serum GDF15 levels can be applied to identify sarcopenia in patients with acute exacerbations of COPD." (PMID 35845807, 2022). "However, we have reported that muscle wasting, including sarcopenia, is a short-term prognostic factor for patients after cardiovascular surgery, and elevation of GDF-15 level reflects muscle wasting as well as renal dysfunction in preoperative cardiovascular surgery patients." (PMID 34063283, 2021). "After a 2-year follow-up, researchers found elevated GDF-15 linked with widespread sarcopenia, but the prediction of incident sarcopenia could not be made." (PMID 34943268, 2021). "Sarcopenia was associated with higher median GDF-15 concentrations than non-sarcopenia patients." (PMID 34943268, 2021). "The circulating factors in sarcopenia group were significantly lower: ALT, AST, ALB, γ-GT, CREA, UA, GLU, TG, LDL, GDF15, TNF-α and IL6." (PMID 40969368, 2025). "Moreover, after reviewing the studies focusing on the relationships between cytokines, growth factors and sarcopenia, many factors, including IL1b, IL6, IL8, IL17 (interleukin‐17), TNFa, TGF1, GDF‐15 (growth differentiation factor‐15) and so on, may all relate to sarcopenia." (PMID 38556722, 2024). "Thus, serum GDF15 levels may accurately predict sarcopenia in COPD patients." (PMID 35845807, 2022). "Recent research has highlighted the pivotal role of growth differentiation factor 15 (GDF15), a member of the transforming growth factor-beta superfamily, in patients with sarcopenia." (PMID 35566740, 2022). "Median GDF-15 levels in patients with/without sarcopenia and with/without frailty were 1916 pg/mL vs. 1569 pg/mL (p = 0.035), and 2252 pg/mL vs. 1438 pg/mL (p < 0.001), respectively." (PMID 41286529, 2025). "In multivariate analysis, high GDF‐15 was found to be an independent predictor for sarcopenia, although not quite statistically significant (OR 1.99, 95%CI 1.00–3.96, p = 0.05)." (PMID 41380167, 2025). "Systemic GDF‐15 was higher in acutely admitted older medical patients with sarcopenia and frailty compared with patients without." (PMID 38890783, 2024).
sarcopenia (continued). "The present data demonstrated that acutely admitted patients with sarcopenia had significantly higher levels of systemic GDF‐15 compared with patients without sarcopenia (P < 0.01)." (PMID 38890783, 2024). "Systemic GDF‐15 was higher in acutely admitted older patients with sarcopenia and frailty compared with patients without." (PMID 38890783, 2024). "Furthermore, insight will be gained from the measurement of GDF15 levels in PLWH after contemporary ART and in the context of accelerated age‐related disorders such as sarcopenia and NAFLD." (PMID 35510313, 2022). "However, while GDF15 shows promise as a biomarker for sarcopenia monitoring, it is not yet employed in clinical routine." (PMID 41441428, 2025). "Still, it is not clear whether GDF‐15 can be utilized as a biomarker of sarcopenia and frailty in the early stages of hospitalization." (PMID 38890783, 2024). "However, the usefulness of c-GDF15 as a biomarker of sarcopenia is still debated, as it is not possible to understand which tissue it comes from." (PMID 38808117, 2024). "GDF15 has been explored in only one study in relation to muscle mass in patients with COPD, and whether circulating GDF15 levels can be used to predict sarcopenia in patients with COPD is unknown." (PMID 35845807, 2022). "However, the tendency is similar as both traumatic acid and GDF‐15 levels progressively elevated in the three groups from younger adults to elderly subjects without sarcopenia, and to elderly subjects with sarcopenia." (PMID 34939349, 2022). "Furthermore, both males and females with sarcopenia had significantly higher GDF-15 levels, compared to those without sarcopenia (males, 1483 ± 1125 pg/mL vs. 3053 ± 2346 pg/m, p < 0.05; females, 891 ± 700 pg/mL vs. 1625 ± 1302 pg/mL, p < 0.05)." (PMID 31581569, 2019). "In addition, preoperative GDF-15 levels were significantly higher in those with than without sarcopenia." (PMID 31581569, 2019). "Furthermore, circulating biomarkers such as growth differentiation factor-15 (GDF15), C-terminal agrin fragment (CAF), neurofilament light chain (NfL), and inflammatory indices have been investigated for their correlation with muscle mass, strength, and sarcopenia status in COPD patients." (PMID 41450343, 2025). "Moreover, it should be recalled that glucocorticoids, either acting dependently or independently of GDF15 signaling, can induce age-related degeneration, such as tissue atrophy/sarcopenia, via pathways which are not dependent on the activation of the immunosuppressive network." (PMID 39643709, 2024). "In older adults with sarcopenia, serum GDF11 levels were significantly elevated compared to non-sarcopenic controls, while GDF15 showed no statistical difference." (PMID 40969368, 2025). "Serum GDF-15, TNFα and IGF-1 levels were compared in patients with and without sarcopenia." (PMID 31581569, 2019). "Recently, studies have introduced muscle-related biomarkers, including growth differentiation factor-15 (GDF-15), GDF-8 (myostatin), activin A, and follistatin that could be used as identifiable markers of sarcopenia, but a lack of studies may limit the confirmation of predictable biomarkers." (PMID 32927586, 2020).
Stroke (62 papers, 2013 to 2026). Sudden impairment of blood flow to a part of the brain due to occlusion or rupture of an artery to the brain. "Mechanistically, GDF-15 is known to modulate inflammatory signaling and has been implicated in preventing post-stroke neural repair by inhibiting cellular proliferation." (PMID 40949500, 2025). "PLATO study also found higher levels of GDF-15 and NT-proBNP were associated with raised risks of bleeding, spontaneous MI, and stroke as well as CV death." (PMID 41348730, 2025). "Longitudinal studies linked blood GDF15 levels with the risk of incident stroke/TIA, although there was some evidence this was related to cardiovascular events." (PMID 39737171, 2024). "In Japanese outpatients with cardiovascular risk factors, GDF-15 was associated with an increased risk of stroke events beyond conventional risk factors and other prognostic markers." (PMID 39008451, 2024). "One key finding was that circulatory GDF15 is closely related to the incidence, severity, and risk of stroke." (PMID 39737171, 2024). "Increased GDF15 was also associated with pro-inflammatory markers and a significantly higher risk for post-stroke depression." (PMID 37715843, 2024). "Concordantly, in a nested prospective biomarker study of the ENGAGE AF-TIMI 48 trial, including 8705 patients, elevated GDF-15 was independently associated with higher rates of stroke and major bleeding." (PMID 39200768, 2024). "By comparison with people in the lowest quartile, patients in the highest quartile of GDF-15 had a significantly increased risk for the primary outcome, HF hospitalization, HF death, MI, stroke, and CV death." (PMID 36676179, 2023). "The ARISTOTLE trail has also pinpointed that increased concentration of GDF-15 is associated with mortality, major bleeding, and stroke in a population with prevalent AF." (PMID 36337899, 2022). "For community-dwelling individuals, GDF-15 was independently related to the composite endpoint of major cardiovascular events, including all-cause stroke and in another study, GDF-15 was associated with atherothrombotic stroke." (PMID 34177769, 2021). "Some investigators reported an increased risk of stroke or systemic embolism at elevated GDF-15 concentrations in AF patients even on oral anticoagulation." (PMID 31280356, 2020). "It was shown that high-sensitivity troponin T (hsTnT) and N‐terminal B‐type natriuretic peptide (NT-proBNP) were independently associated with stroke and systemic embolism, and hsTnT and growth differentiation factor-15 (GDF-15) with major bleeding." (PMID 32780327, 2020). "In ENGAGE AF-TIMI 48 trial, GDF-15 levels elevating from the baseline of 1661 pg/mL to 12 months of 1711 pg/mL were independently associated with a twofold higher rate of stroke or systemic embolic events in AF patients." (PMID 33115406, 2020). "Our study shows that GDF-15 levels at admission are associated with post-stroke mortality even after adjustment for other usual predictors, although the improvement of prediction compared with a clinical model was only limited." (PMID 31258506, 2019). "In a context of growing interest to discover new biomarkers in stroke, we aimed to assess the association between circulating GDF-15 levels and three-month mortality in ischemic stroke patients treated with acute revascularization therapy." (PMID 31258506, 2019). "Patients with higher GDF-15 levels had a higher risk of future stroke and all-cause death." (PMID 40949500, 2025). "Interestingly, GDF15 on admission correlated with depression scores at 90 days and was predictive of post-stroke associated depression." (PMID 39737171, 2024). "Current knowledge associates GDF15 with potential cardioprotection; however, its role in stroke-induced cardiac dysfunction remains to be determined, and whether it constitutes a deleterious or cardioprotective factor in this context." (PMID 39008451, 2024). "GDF15 has also been shown to associate with stroke, bleeding, and mortality in AF patients." (PMID 39434187, 2024).
Stroke (continued). "The association of GDF-15 with the outcome of stroke needs to be further studied." (PMID 36844747, 2023). "In the ARISTOTLE (Apixaban for Reduction in Stroke and Other Thromboembolic Events in Atrial Fibrillation) trial, GDF-15 was shown to be an independent risk factor not only for major bleeding complications but also for mortality and stroke in AF patients randomized to either warfarin or apixaban." (PMID 36836162, 2023). "As for stroke, associated biomarkers were GDF-15, NT-proBNP and CRP." (PMID 34935094, 2022). "In addition, in patients with atrial fibrillation, increased GDF-15 levels are associated with major bleeding, mortality, and stroke." (PMID 35628490, 2022). "It has also been suggested that GDF15 could be used as a prognostic tool for stroke risk in patients with AF." (PMID 34445593, 2021). "However, the ARISTOTLE large-scale trial reported GDF15 as a risk factor for major bleeding, mortality, and stroke in patients with permanent AF." (PMID 34798808, 2021). "This study provides data linking NT-proBNP and GDF-15 with prothrombotic blood alterations, which might support the concept of a value of the biomarkers in the estimation of stroke risk in AF." (PMID 31280356, 2020). "In a more clinical context, GDF-15 could be used as a biomarker to predict stroke risk in hypertensive patients as well as mortality and stroke risk in atrial fibrillation." (PMID 31258506, 2019). "We observed that GDF-15 levels at admission were associated with post-stroke mortality even after adjustment for multiple variables such as NIHSS score which is a very useful scale for prognosis evaluation after stroke and even after adjustment for other usual predictors." (PMID 31258506, 2019). "In addition to clinical characteristics, biomarkers shown to improve bleeding and/or stroke risk estimates are also part of the clinical scores, such as NT-proBNP, high-sensitivity cardiac troponin T (hsTnT), growth differentiation factor-15 (GDF-15), hemoglobin level and platelet count." (PMID 31731710, 2019). "Reparative microglia produce neurotrophic factors, including osteopontin (OPN), insulin-like growth factor 1 (IGF1), fibroblast growth factors (FGFs), hepatic growth factor, and growth differentiation factor 15 (GDF15), within a few days following a stroke." (PMID 40098163, 2025). "Tuberculous meningitis was also shown to correlate with increased GDF15 levels, which were further elevated in those with radiographic evidence of a stroke." (PMID 40019842, 2025). "Remarkably, GDF15 emerged as the top-risk protein for CVD, stroke, dementia, depression and mortality." (PMID 39753750, 2025). "While our findings shed light on GDF15 post-stroke expression pattern, its intricate cardiac functions in the aftermath of a stroke are yet to be fully elucidated." (PMID 39008451, 2024). "It was also evident that blood GDF15 at time of admission was consistently elevated in stroke patients who later displayed poorer modified Rankin Scores (mRS) both at discharge and 90 days follow up." (PMID 39737171, 2024). "The biomarker substudy in the ARISTOTLE trial with apixaban has demonstrated that GDF-15 alone and in addition to cTnI are predictive of major bleeding, mortality, and stroke in AF patients." (PMID 38643439, 2024). "Our experimental data support previous observation that GDF15 circulating levels rapidly increase in the circulation following an experimental IS, aligning with the elevated levels of GDF15 observed in stroke patients." (PMID 39008451, 2024). "Together with blood biomarker findings highlighted above, these studies indicate that GDF15 serves as a putative stroke biomarker, although future work should elaborate further on the source of centrally induced GDF15." (PMID 39737171, 2024). "Our findings suggest that both the GDF15 gene and pro-protein are expressed in the ischemic brain after a stroke, while only its mature form is expressed remotely in in the heart." (PMID 39008451, 2024).
Stroke (continued). "Key proteins involved in mitochondrial stress, such as ATF5, ATF4, HSF1, FGF21, and GDF15, hold promise as potential targets for modulating neuroinflammation during stroke." (PMID 38321473, 2024). "The mature form of GDF15 was exclusively detected in the heart, displaying a significant 75% increase in both left and right stroke groups compared to the sham group." (PMID 39008451, 2024). "GDF-15 is also related to clinical outcomes, including mortality, major bleeding, and stroke, in patients with AF." (PMID 37396418, 2023). "Highest hazard ratios were observed for CRP, HbA1c and GDF-15, with hazard ratios above 2.4 for MI, and above 1.6 for stroke, when comparing highest to lowest quartile levels of these markers." (PMID 34935094, 2022). "All five markers showed associations with long-term risk of CVD (NT-proBNP, CRP, HbA1C and Cystatin-C for MI; GDF-15, NT-proBNP and CRP for stroke)." (PMID 34935094, 2022). "Serum GDF-15 has been consistently identified as a predictor of stroke, mortality and bleeding in atrial fibrillation, either alone or included in an ABC (Age, Biomarkers, Clinical history) risk score." (PMID 34441356, 2021). "A study enrolling 310 Chinese patients that experienced an ischemic stroke reported that GDF-15 exacerbated the development of post stroke depression." (PMID 34942914, 2021). "Likely, after 1.9 years of follow-up in ARISTOTLE trial, an annual rate of stroke or systemic embolic events was 2.03% in AF patients with the highest quartile of GDF-15 (> 2052 ng/L) compared to 0.90% in those with the lowest quartile of GDF-15 (≤ 977 ng/L)." (PMID 33115406, 2020). "To conclude, our study is the first providing data on GDF-15 time course in the plasma of post-stroke patients undergoing revascularization, either by thrombolysis or mechanical thrombectomy." (PMID 31258506, 2019). "Growth differentiation factor-15 was increased to an immeasurably high level on the day of the stroke-like episode." (PMID 31630688, 2019). "Background and Aims: Growth differentiation factor-15 (GDF-15) has been identified as a robust marker of developing cardiovascular disease, however, little is currently known about its prognostic value in stroke patients." (PMID 31258506, 2019). "We measured growth differentiation factor-15 and multiple amino acids in his blood, longitudinally during and after the stroke-like episode." (PMID 31630688, 2019). "After adjustment also for other biomarkers the incremental rise in outcome events by one SD increase of log GDF-15 remained significant for all events except stroke." (PMID 24312445, 2013). "Clinical studies show that higher baseline GDF-15 predicts adverse events at 3 months post-stroke, independent of traditional risk factors, age, and stroke severity." (PMID 41590509, 2026). "However, the predictive value of GDF-15 for stroke remains uncertain, and current evidence is insufficient to establish a clear association." (PMID 41590509, 2026). "In hypertensive patients without prior stroke, higher plasma GDF-15 concentrations are correlated to an increased risk of first-ever ischemic stroke over follow-up periods of several years." (PMID 41590509, 2026). "Future studies with larger patient cohorts and a greater number of events will be important to evaluate whether GDF15 can accurately predict specific cardiovascular outcomes including MI and stroke individually." (PMID 40723863, 2025). "In this study, GDF15 level was associated with elevated serum ferritin (> 2500 μg/L), previous stroke and splenectomy, but not with frequency of sickle cell crises, PAH, or hydroxyurea usage in these patients." (PMID 40019842, 2025). "Of note, GDF15 was one of the top biomarkers for all conditions except stroke and cancer." (PMID 39695064, 2025). "Besides stroke, examination of GDF15 in neurotrauma-induced degenerative conditions in human populations was limited." (PMID 39737171, 2024).